FMC1 (formation of mitochondrial complex V assembly factor 1)
Description:
Plays a role in the assembly/stability of the mitochondrial membrane ATP synthase (F(1)F(0) ATP synthase or Complex V).
Synonyms: C7orf55; HSPC268
Tractability: PROTAC: ubiquitination databases record sites on it.
Gene: Protein-coding gene on chromosome 7 (139,339,457 to 139,346,328, forward strand). Ensembl gene ENSG00000164898.
Subcellular location: Mitochondrion
Subcellular location (Human Protein Atlas): Mitochondria
Gene Ontology:
Molecular function: protein binding
Biological process: mitochondrial proton-transporting ATP synthase complex assembly
Cellular component: mitochondrion
Genetic constraint (gnomAD): Loss-of-function variants: 6 observed, 11.4 expected, observed/expected ratio (o/e) 0.53, 90% interval 0.29 to 1.04. The upper end of that interval is the gene's LOEUF score, 1.04, which puts it in group 4 of 6, group 1 being the genes least tolerant of losing a copy. Missense variants: 146 observed, 160.34 expected, observed/expected ratio (o/e) 0.91, 90% interval 0.8 to 1.04. Synonymous variants: 59 observed, 64.19 expected, observed/expected ratio (o/e) 0.92, 90% interval 0.75 to 1.14.
Homologues: Orthologues: rat Fmc1 (95% identical), pig FMC1 (94% identical), dog FMC1 (93% identical), mouse Fmc1 (93% identical), guinea pig FMC1 (88% identical), tropical clawed frog fmc1 (71% identical), zebrafish si:ch1073-314i13.4 (45% identical), Drosophila melanogaster CG34117 (36% identical), Caenorhabditis elegans C29E4.12 (31% identical).